CD44 (CD44 molecule (IN blood group))
Diseases named in the same sentence as CD44 in open-access papers (continued):
Sharing a sentence is not in itself a finding about the gene and the disease.
colorectal tumors (continued). "However, although the present data suggest that targeting Pin1 in CD44+CD133+ colorectal tumor-initiating cells is a promising therapeutic approach, there are some limitations regarding the use of Pin1 inhibitors for treating human disease." (PMID 35433695, 2022). "Similarly, PrPC was also shown to influence the proliferation of human CSCs in which a population of CD44+/PrPC+ cells was isolated from primary colorectal tumors, showing an enhanced tumor-initiating and metastatic ability." (PMID 27229535, 2016). "Furthermore, CD44+CD133+ cell population has been reported to enrich in colorectal tumor-initiating cells." (PMID 27302922, 2016). "We also analyzed other markers, including the gastric and colorectal tumor markers CD44 and CD133." (PMID 25819560, 2015). "Although the 5-FU treatment could effectively inhibit colorectal tumor growth, we observed an enrichment of CSCs in 5-FU-treated tumors supported by the upregulation of CSC markers (CD44, SOX2), which could be responsible for the observed chemoresistance." (PMID 36827121, 2023). "EpCAMhigh/CD44+ double-positive cells were not present in the normal intestinal mucosa adjacent to colorectal tumors." (PMID 24765173, 2014). "In all colorectal tumors we have investigated to date, tumors can be successfully transplanted using small numbers (e.g. <1,000) of cells phenotypically positive for both epithelial-specific antigen (i.e. ESA or EpCAM) and CD44." (PMID 18560594, 2008). "Furthermore, data of immunohistochemical analysis demonstrated that baicalin treatment in vivo enhanced the expression of E-cadherin and reduced the expressions of Ki67, Vimentin, N-cadherin, CD133 and CD44 by comparing with negative control in HCT116 orthotopic transplanted colorectal tumors." (PMID 32127957, 2020). "Of the human colorectal tumour cell lines examined in this study, HCT116, HT29, CCL-228 and DiFi cells were highly CD44 positive (i.e. >95% of tumour cell populations), while CCL-225 and Colo-2 cells were CD44 negative." (PMID 30899442, 2019).
gastric adenocarcinoma (23 papers, 2012 to 2025). "Next, to investigate the clinical correlation between NINJ2 and CD44 levels, we analyzed data from human gastric adenocarcinoma samples (n = 426) in The Cancer Genome Atlas (TCGA) and the oncoSG dataset using cBioPortal." (PMID 40518514, 2025). "Our data demonstrate the presence of a subset of cells with a CD24+CD44+CD54+EpCAM+ phenotype in gastric adenocarcinomas from 127 patients." (PMID 36737794, 2023). "In gastric adenocarcinoma, cancer stem cell-like cells are activated, and CD44 is used as a marker in conjunction with MEK to evaluate prognostic indicators of gastric adenocarcinoma patients undergoing gastrectomy." (PMID 36316684, 2022). "A pattern of CD44+ high/CD24+ low expression is a cardinal character of cancer stem cell activity in gastric adenocarcinoma." (PMID 33233485, 2020). "In our previous study, gastric CSCs were identified and isolated from tumor tissues and peripheral blood of gastric adenocarcinoma patients through the expression of the CSC markers CD44 and CD54." (PMID 32831823, 2020). "Changes in CD44 expression are typically one of the latest manifestations in the malignant development of gastric adenocarcinoma." (PMID 30909497, 2019). "In this study, we initially sorted MKN-45 gastric adenocarcinoma cells, in terms of determining the cells with CD44 surface marker." (PMID 27895854, 2016). "CD44 is a transmembrane glycoprotein involved in cellular adhesion, which has also been shown to be highly expressed in gastric adenocarcinoma." (PMID 25212506, 2014). "CD44 was also highly expressed in gastric adenocarcinoma and its expression correlated with poor prognosis in patients with the intestinal type of gastric adenocarcinoma." (PMID 22839505, 2012). "In that study, expression of CD44 correlated with a poor prognosis in patients with the intestinal type of gastric adenocarcinoma." (PMID 22839505, 2012). "Upon its administration to GCSCs and CD44+ cells sorted from human gastric adenocarcinoma cell line (AGSs), a significant decrease in the proportion of CD44+ cells, in the ability of mammosphere and colony formation, and in the growth of GCSC mammosphere were observed." (PMID 41009762, 2025). "In addition, GAPLINC is a gastric adenocarcinoma–related lncRNA that positively regulates CD44 in various cancers." (PMID 38586313, 2024). "Gastric adenocarcinoma-associated, positive CD44 regulator, long intergenic noncoding RNA (GAPLINC), a new lncRNA, is abnormally highly expressed in many human tumors and participates in the regulation of malignant biological behavior of tumors." (PMID 34722262, 2021). "Gastric adenocarcinoma-associated, positive CD44 regulator, long intergenic noncoding RNA (GAPLINC) is a recently identified lncRNA that can actively participate in the tumorigenesis of various cancers." (PMID 34722262, 2021). "A lncRNA, gastric adenocarcinoma predictive long intergenic noncoding RNA (GAPLINC), also induces CD44 expression by suppressing miR-221, a CD44-targeting miRNA." (PMID 32168951, 2020). "The role ofALX-4 expression was evaluated in CD44+GCSCs, isolated from MKN-45 gastric adenocarcinoma cell line, to determine the therapeutic effect of this protein, particularly for drug resistant tumors." (PMID 27895854, 2016). "This study was performed in order to evaluate CD44 and CD133 expressions by immunohistochemistry in 95 primary gastric adenocarcinoma and their relation to clinical and pathological parameters of these tumors." (PMID 25635255, 2014). "Thus, we believed that the clusters of CD44(+)CD45(+) cells isolated from tumor tissues and peripheral blood of gastric adenocarcinoma patients were gastric CSCs." (PMID 32831823, 2020). "CD44 and CD24 expression levels were investigated immunohistochemically in tumor samples from 290 patients with non-cardia gastric adenocarcinoma, of whom 77 had paired adjacent normal gastric mucosa." (PMID 25212506, 2014).
rheumatoid arthritis (22 papers, 2005 to 2025). A chronic, systemic autoimmune disorder characterized by inflammation in the synovial membranes and articular surfaces. "In murine models of rheumatoid arthritis and allergic dermatitis, leukocytes of CD44-deficient mice showed reduced ability to adhere tightly to the endothelium, reduced neutrophil influx and decreased severity of inflammation." (PMID 31226944, 2019). "Even more, soluble glycoproteins in the medium deserve attention, too, as the instructive example of the neutralizing effect of a variant of CD44 and fibrin(ogen) on Gal-8’s pro-apoptotic activity on synovial fluid cells in rheumatoid arthritis attests." (PMID 29934665, 2018). "CD44 is linked to many diseases, for example rheumatoid arthritis, cancer metastasis and systemic lupus erythematosus." (PMID 26379032, 2015). "Functional aspects of alternative splicing of CD44 caused by its polymorphism have been implicated in rheumatoid arthritis." (PMID 21933395, 2011). "The selectins, along with very late antigen-4 and CD44, have been implicated in mediating leukocyte rolling interactions that lead to joint recruitment and inflammation during the pathogenesis of rheumatoid arthritis." (PMID 16207337, 2005). "The 5MER peptide was originally derived from a sequence of a pro‐inflammatory CD44 variant isolated from the synovial fluid of a rheumatoid arthritis (RA) patient." (PMID 37897137, 2023). "CD44 was also found to serve as a ligand for GAL-8 in synoviocytes from rheumatoid arthritis patients." (PMID 37898403, 2023). "The binding of soluble fibrinogen and CD44 to GAL-8 prevented the pro-apoptotic activity of this lectin in inflammatory synoviocytes from rheumatoid arthritis patients, resulting in enhanced inflammatory responses." (PMID 37898403, 2023). "Blocking the binding of HA to CD44 significantly reduced the severity of inflammatory diseases, such as rheumatoid arthritis, autoimmune diabetes, and allergic encephalomyelitis, but there is still lack of evidence that supports their role in CP/CPPS." (PMID 35693826, 2022). "Targeting CD44 with therapeutics has shown potential in rheumatoid arthritis and various methods of modulating the CD44-HA interaction have been assessed in cancer therapy." (PMID 26379032, 2015). "This work proved that the presence of LGALS9, PTPRC and CD44 in platelets could serve as a clinical indicator of rheumatoid arthritis." (PMID 35563556, 2022). "For instance, the degradation products of high-molecular-weight hyaluronic acid activate TLR2/4 and cluster of differentiation 44 (CD44), thereby promoting the inflammatory process in obesity and rheumatoid arthritis (RA)." (PMID 40877572, 2025). "In line with our observation, in a murine model of rheumatoid arthritis, treatment of mice with IM7.8.1 anti-CD44 antibody was accompanied by a significant increase in serum CD44 level compared to baseline level (Day 0)." (PMID 39411720, 2024). "In synovial fluid cells from rheumatoid arthritis patients, GAL-8 was identified as a high-affinity ligand of CD44, showing special binding activity to CD44vRA, the splicing variant found in this fluid." (PMID 37898403, 2023). "The interaction of rhPRG4 and CD44 on the surface of rheumatoid arthritis fibroblast-like synoviocytes (RA-FLS) results in inhibition of nuclear factor kappa B (NFκB) nuclear translocation and inhibition of proinflammatory-cytokine-induced RA-FLS proliferation." (PMID 26643105, 2015).
invasive breast carcinoma (21 papers, 2009 to 2025). A carcinoma that infiltrates the breast parenchyma. "In consistent with our findings, a study showed that invasive breast cancer that express high levels of PD-L1 expressions positively regulate cancer stem cells that express CD44 high, CD24 low and OCT4high." (PMID 36604635, 2023). "Several studies have shown a significant relationship between CD44 and invasive breast cancer, although they were using advanced molecular methods, which is not generally practical, and did not specifically describe investigating the role of CD44v6 in IBC-NST." (PMID 34925920, 2021). "Consistent with our study, another study that included fifty randomly selected cases of invasive breast carcinoma showed that tumors with CD44+/CD24−ve BCS cells had a higher rate of recurrence/metastasis (41.2% versus 28.6%, P=0.03)." (PMID 32684928, 2020). "Immunohistochemical analysis allowed us to evaluate the expression of vimentin, ER, Ki67, CD44 and TGFβ with respect to the presence of BOLCs in breast-infiltrating carcinoma." (PMID 30327566, 2018). "As it is known, the MDA-MB-231 cell line is used as a model of invasive breast cancer, expressing high levels of CD44 and binding HA efficiently." (PMID 30564299, 2018). "In contrast, a CD44(-) CD24 (+) phenotype is a poor prognostic marker in early invasive breast cancer." (PMID 24392029, 2013). "CD44 is a compelling biomarker present in invasive breast cancer." (PMID 36120232, 2022). "CD44 is a marker of tumour-initiating cells and is upregulated in invasive breast carcinoma; however, its role in the cancer progression is unknown." (PMID 19240712, 2009). "Although our study has some limitations, such as its retrospective design and relatively small number of studied patients, the data obtained indicate that EGFR and CD44 could serve as useful biomarkers for better determination of the prognosis of invasive breast cancer." (PMID 25429827, 2015). "The expression of DLL3 on the tumor tissues of patients with invasive breast cancer can promote the infiltration of immune cells, including plasma cells, CD8 T cells, CD44 memory-activated cells, macrophages, and T regulatory cells." (PMID 36428765, 2022). "We found that expressions of BMP-2 and CD44 were significantly upregulated, whereas expressions of RB1 and CDH1 (E-cadherin) were significantly downregulated in invasive breast cancer." (PMID 28725489, 2017). "In lesions of invasive breast cancer, Mylona and colleagues showed a correlation between the CD44+/CD24- immunophenotype and negative lymph node metastasis and lower staged tumors." (PMID 23419168, 2013). "Additionally, the CD44 expression in diverse cancer pathological stages was analyzed based on GEPIA database, as a result, CD44 expression related to the clinical pathological stages of breast invasive carcinoma (BRCA), pancreatic adenocarcinoma (PAAD), skin cutaneous melanoma (SKCM), and STAD." (PMID 38590654, 2024).
laryngeal carcinoma (21 papers, 2012 to 2026). Carcinoma that arises from the laryngeal epithelium. "CD44 has also been associated with worse tumor grade/staging and prognosis in pharyngeal and laryngeal cancers." (PMID 41466485, 2026). "Among the most extensively researched CSC markers in laryngeal cancer are CD44 and the aldehyde dehydrogenase 1 family member A1 (ALDH1A1)." (PMID 39452555, 2024). "The expression of CD44 in laryngeal carcinoma and its clinical importance have been the subject of numerous investigations." (PMID 39452555, 2024). "It has been suggested that the co-expression of ALDH1A1 and CD44 is a more precise marker for locating CSCs in laryngeal cancer." (PMID 39452555, 2024). "Several other potential CSC markers have been studied in laryngeal cancer, in addition to CD44 and ALDH1A1." (PMID 39452555, 2024). "Laryngeal cancer tissues are characterized by a considerable increase in CD44 expression when compared to nearby normal tissues." (PMID 39452555, 2024). "Increased expression of CD44 was indicated as an independent predictor of a poor prognosis in early-stage laryngeal cancer." (PMID 39452555, 2024). "Downregulation of miR-203 leads the laryngeal carcinoma cells to acquire stem-cell traits, such as CD44+." (PMID 36140250, 2022). "Additional markers associated with stemness in laryngeal carcinoma include the expression of aldehyde dehydrogenase (ALDH) and the cell-surface glycoprotein CD44+." (PMID 36140250, 2022). "Only the mRNA expression of CD44 has been shown to be a significant predictor of local recurrence after RT in early stage laryngeal cancer." (PMID 36261806, 2022). "In this study, we identified and isolated ALDH+ and CD44+ CSC from laryngeal cancer cells as an approach to better predict the role of IL-6 in chemo-drug resistance." (PMID 28878571, 2017). "Furthermore, patients with laryngeal cancer had a poorer prognosis when CD44+/ALDH1A1+ cells were present." (PMID 39452555, 2024). "CD44 expression is a potential marker for more aggressive forms of laryngeal cancer." (PMID 37173926, 2023). "There are few data on the prognostic role of CD44 expression in laryngeal carcinomas." (PMID 37173926, 2023). "As previously reported for the oral cavity and oropharynx, low CD44 expression is correlated with increasing metastasizing behavior and poor prognosis, while in laryngeal carcinomas, high CD44 expression is correlated with increasing metastasizing behavior and radiotherapy resistance." (PMID 37173926, 2023). "Our results here reveal CD44 expression in 64.1% of laryngeal carcinomas, almost half of which exhibited lymph node metastases at the time of diagnosis, confirming its role in the selection of cancer stem cells, inducing disease progression and therapy resistance." (PMID 37173926, 2023). "In addition, CD44 is a biological factor that is significantly correlated with response to RT, in patients with early stage laryngeal cancer." (PMID 36261806, 2022). "CD44 levels have also been correlated with clinical response to radiotherapy and may predict local recurrence in patients with early-stage laryngeal cancers and local recurrence and progression-free survival in oropharyngeal SCC." (PMID 32588101, 2021). "In addition, some investigators demonstrated that CD44 had the potential to predict local recurrence of laryngeal cancer after radiotherapy." (PMID 28262804, 2017). "To investigate whether CD44 percentage correlates with cisplatin resistance in laryngeal carcinoma; we chose three laryngeal carcinoma cell lines namely, UM-SCC-10B, UM-SCC-15s (the cisplatin resistant pair of UM-SCC-10B) and UM-SCC-74B." (PMID 27276062, 2016). "Thus, CD44 expression is a potential marker for more aggressive forms of laryngeal cancer." (PMID 37173926, 2023). "However, previous studies in laryngeal carcinoma suggested that PLOD2 enhanced CD44 expression via activation of the Wnt-signaling pathway, which may be a possible explanation for GBM as well." (PMID 35682709, 2022).
laryngeal carcinoma (continued). "In laryngeal carcinomas in particular, it has been revealed that cancer stem cells expressing the isoform v3 of CD44 surface antigen seem to have the ability for lymph node metastasis while those expressing the isoform v6 of CD44 seem to have ability for distant metastasis." (PMID 23031716, 2012). "Findings from recent studies have revealed that CSC can be identified and isolated through distinct cell surface markers, such as CD44 and CD133, which are found in laryngeal carcinoma cells." (PMID 28878571, 2017). "In fact, about 95% of the three laryngeal carcinoma lines in this study (UM-SCC-10B, UM-SCC-15s, and UM-SCC-74B) is overwhelmingly CD44+ underscoring the need for ancillary marker(s) to pinpoint residual cells/TPCs." (PMID 27276062, 2016). "Decreased CD44 expression was also observed in non-tumor epithelium adjacent to oral and laryngeal cancers, suggesting an early role for CD44 in carcinogenesis." (PMID 36428690, 2022). "However, neither CD44 nor CD44-v6 was correlated with the 3-year OS rate in patients with laryngeal cancer, which implies that a longer follow-up time is needed for head and neck patients." (PMID 24410905, 2014).
renal cell carcinoma (20 papers, 2001 to 2025). "The protein expression of CD44 has been studied in renal cell carcinoma, and higher expression is associated with poor prognosis." (PMID 38724670, 2024). "In renal cell carcinoma, an association between CD44 and stage, grade, and poor prognosis was observed." (PMID 35274800, 2022). "In renal cell carcinoma, CD44 expression has also been linked to poor prognosis." (PMID 40851082, 2025). "Chronically exposed cells also exhibited an induction of CD44, a cell surface marker commonly found in renal cell carcinoma, as well as in tubular repair in chronic renal injury such as chronic kidney disease." (PMID 40558504, 2025). "An increase in endothelin receptor type B, phospho-S6 and CD44 expression and more frequent overexpression in metastases than in corresponding primary renal cell cancers were shown." (PMID 32668608, 2020). "Here, we isolated CD44+/CD105+ HuRCSCs from patients with renal cell carcinoma." (PMID 36860916, 2023). "CD44 is the most frequently reported marker of the cancer stem cells in renal cell carcinoma (RCC)." (PMID 36079127, 2022). "Whether RSK4 can mediate the invasion and metastasis of renal cell carcinoma by CD44 and MMP-9 is a new direction proposed by this study." (PMID 32209138, 2020). "CD44 is a marker of cancer stem-like cells in renal cell carcinoma (RCC)." (PMID 26287771, 2015). "Two renal cell carcinoma cell lines (49RC 43STR and 75RC 2STR) were characterized by detection of the cell surface proteins: CD44(var), intercellular adhesion molecule-1 (ICAM-1), urokinase-type plasminogen activator (uPA) and its receptor and aminopeptidase N (APN)." (PMID 11556847, 2001). "Thus, CD44 is a common marker of various types of cancers, including renal cell carcinoma." (PMID 40558504, 2025). "CD44 and MMP9 are frequently utilized as immunohistochemical markers that are concurrently evaluated in renal cell carcinoma (RCC) and have been identified as potential molecular prognostic markers for RCC." (PMID 37509716, 2023). "CD44, MMP-2, and MMP-9 are new potential molecular prognostic markers in renal cell carcinoma (RCC)." (PMID 36831550, 2023).